TLR9 (toll like receptor 9)
Diseases named in the same sentence as TLR9 in open-access papers (continued):
Sharing a sentence is not in itself a finding about the gene and the disease.
viral infection (continued). "The impaired liver responses observed in 3d mice that were not apparent in TLR9 or TLR7-deficient mice suggests that a level of redundancy unique to innate immunity is in place within infected tissue sites to rapidly respond to viral infection." (PMID 22723955, 2012). "In viral infection models, DHM interacts specifically with Toll-like receptor 9 (TLR9) to suppress activation of inflammatory transcription factors, thereby reducing cytokine release during herpes simplex virus infection." (PMID 41415577, 2025). "Members of the TLR family that have been shown to be involved in responses to viral infection, in part including that of SARS-CoV-2, are TLR1, TLR2, TLR3, TLR4, TLR6, TLR7, TLR8 and TLR9." (PMID 41011507, 2025). "The convergence of TLR-9 signaling and EBV presence introduces intriguing prospects of crosstalk between viral infection and immune activation." (PMID 37894471, 2023). "Accumulation of LDs facilitates early innate response to viral infection through modulation of interferon signaling, in part via TLR7 and TLR9 pathways." (PMID 37298680, 2023). "LILRA4 is a coreceptor that controls innate immune responses generated through FCER1G in viral infection and acts as a negative regulator of TLR7 and TLR9 signaling cascades." (PMID 37435086, 2023). "During viral infection, pDCs function as professional antigen-presenting cells and utilize TLR7 and TLR9 as crucial components of their endosomal nucleic acid sensing mechanism, thus allowing them to detect the presence of bacterial and viral nucleic acids." (PMID 38116008, 2023). "Human pDCs, like murine pDCs, respond to viral infections and produce type 1 interferon in response to TLR7 and TLR9 and type 3 interferons in response to TLR9." (PMID 35163401, 2022). "We evaluated the effect of the activation of the different pathways (TLR9, STING, STAT6) due to viral infections on the cytokine and chemokine expression by primary NK cells." (PMID 32140147, 2020). "The crucial role of pDCs in antiviral responses involves sensing viral infection through TLR7 and TLR9, which results in the production of large amounts of IFN-I." (PMID 31093508, 2019). "The propagated importance of pDC for early sensing of viral infection is supported by the high transcription rate of TLR3, TLR7, and TLR9 found in bovine pDC." (PMID 30425716, 2018). "Here, we showed that Blimp-1 was induced in pDCs, the professional IFN-I producing cells that limit viral infection, after TLR7 and TLR9 stimulation." (PMID 30131810, 2018). "In this study, we focused on TLR1, TLR2, TLR4, TLR5, TLR6 and TLR9 expression fold changes in two genital epithelial cells (HEC-1-A and VK2) after viral infection." (PMID 30419930, 2018). "In viral infection, both host cell membrane-localized TLRs (TLR2, TLR4, detecting viral envelope proteins) and endosomal TLRs (TLR3, TLR7, TLR8, and TLR9, nucleic acid sensors) initiate signal transduction cascades leading to IFN production." (PMID 28382038, 2017). "Previously, it was shown that intravenous application of TLR9 agonist induces clusters of professional antigen-presenting cells in the liver, which support CD8 T cell expansion in viral infection." (PMID 29038654, 2017). "pDCs play a key role at the interface of innate and acquired immunity in anti-viral responses by sensing viral infection through Toll-Like Receptors (TLRs) TLR7 and TLR9, which results in the production of large amounts of type-I interferons (IFNs)." (PMID 28052019, 2017). "Like type I IFNs, type III IFNs are induced in viral infection by the PRR RIG-I as well as TLR3 and TLR9 and rely on the activation of the same transcriptional activators, including IRF3, IRF7, and NFκB." (PMID 28382038, 2017). "Given the key role of type I IFN in virus infection, type I IFN-inducing TLR9 ligands is likely to contribute to the rapid induction of innate immune responses by enhancing TLR9 expression." (PMID 28266597, 2017).
viral infection (continued). "Plasmacytoid dendritic cells (pDCs) are a unique subset of naturally occurring dendritic cells, which triggers the production of large amounts of type I interferons (IFNs) after viral infections through Toll-like receptor (TLR) 7 and TLR9." (PMID 28052019, 2017). "Albeit a role of TLR3 in NK cells during viral infections is still elusive, yellow fever vaccination was able to enhance detection of TLR3 and TLR9 in NK cells early after vaccination, suggesting its role as an activation marker for NK cells." (PMID 29038620, 2017). "pDCs represent by far the major type I IFN-producing cells in vivo in response to viral infections, during autoimmunity and even bacterial infection, through TLR7/ and TLR9/MyD88 sensing of nucleic acids." (PMID 27792766, 2016). "Plasmacytoid dendritic cells (pDCs) are known to produce a large amount of type I IFNs upon viral infection through the TLR7 and TLR9 system." (PMID 26384031, 2015). "pDCs express TLR7 and TLR9 and are capable of producing large amounts of IFN-I and upregulating MHC class II and costimulatory molecules such as CD80 and CD86 in response to viral infections or TLR stimulation." (PMID 26263178, 2015). "CpG-DNA recognized by Toll-like receptor 9 (TLR9) on DCs arouses many immune diseases (such as cancer, viral infection, and autoimmune disorders)." (PMID 24696007, 2014). "For example, it has been shown that viral infections can activate a broader set of intracellular innate immune receptors, such as TLR7 or TLR9." (PMID 24744264, 2014). "In fact, it is now known that one of the most effective vaccines, the live-attenuated yellow fever vaccine, activates multiple DC subsets through TLR2, TLR7/8 and TLR9, which leads to a robust balanced immune response." (PMID 26344621, 2014). "ICP0 plays a key role in blocking IFN-induced inhibition of viral infection as well as the TLR2/TLR9-mediated inflammatory cytokine response to HSV infection." (PMID 24979708, 2014). "PDCs are highly specialized immune cells that produce large amounts of type I IFNs in response to viral infection via, in part, TLR7 and TLR9." (PMID 24039973, 2013). "TLR-1, TLR-2, TLR-3, TLR-7, TLR-8, TLR-9, and TLR-10 induce type 1 IFN production during viral infections." (PMID 22114589, 2011). "pDCs play a vital role in the generation of innate and adaptive immunity following viral infection, primarily through the production of large quantities of IFNα in response to stimulus of TLR7 or TLR9 PRRs by ssRNA or DNA PAMPs, respectively." (PMID 20532161, 2010). "In response to systemic viral infection, pDCs produce type I IFNs by recognizing viral nucleic acids through TLR7 and TLR9, while production of type I IFNs in cDCs depends on RLH and cytosolic DNA sensors." (PMID 19479062, 2009). "In response to viral infection, pDC further increase IFN production via TLR7 and TLR9 pathways, leading to increased pDC migration and maturation." (PMID 19830165, 2009). "In addition, two independent studies demonstrated that during viral infections, such as DENV or SARS-CoV-2, TLR9 recognizes mitochondrial (mt) DNA that is released into the cytosol, leading to NF-κB activation and an antiviral immune response." (PMID 40791597, 2025). "Cells were stimulated with Staphylococcal enterotoxin B (SEB) as a TCR stimulus, with or without CpG2216—an oligonucleotide that activates TLR9 and induces IFNa, mimicking viral infection." (PMID 40834853, 2025). "Tlr9–/–;Mavs–/– double-knockout mice phenocopied Tlr9–/–;Rigi–/– mice, as they demonstrated no survival advantage of influenza A challenge following Pam2ODN treatment, indicating a critical role for MAVS signaling in inducible resistance to viral infection." (PMID 39352770, 2024). "This is dependent on both TLR9 and type I IFN signaling, and inhibition of TLR9, MyD88, and NF‐κB at various phases in the innate response pathways can prevent the activation of capsid‐specific CD8+ T cells during virus infection." (PMID 37773693, 2023).
viral infection (continued). "Epstein–Barr virus infection can alter the m6A-modified epitranscriptome of host B cells and upregulate mRNA and protein levels of fas cell surface death receptor (FAS) but downregulate toll-like receptor 9 (TLR9), which are related to apoptosis and virus infection." (PMID 37671161, 2023). "Since type I IFN signaling is critical for protection against several viral infections, rASP-1 stands to be a new addition to other known type I IFN stimulating adjuvants such as Poly I:C (TLR3 agonist), R848 (TLR7/8 agonist), CpG (TLR9 agonist) and STING agonists." (PMID 36119026, 2022). "Since B cells primarily express TLR7 and TLR9, we specifically discuss the role of Toll-like receptor (TLR)-mediated B cell responses to viral infections and their role in augmenting adaptive immunity through enhanced cytokine production and antigen presentation." (PMID 34293057, 2021). "Sex differences in TLR9 expression has also been reported in mice, where male mice showed higher expression of TLR9 and higher activation of innate immune system with higher numbers of infiltrating neutrophils upon MCMV viral infection but similar viral load between male and female." (PMID 33519463, 2020). "In response to a viral infection, pDCs can recognize viruses through toll-like receptor 7 (TLR7) and toll-like receptor 9 (TLR9) signaling and rapidly produce type I interferons (IFNs), which can lead to robust CD8+ T cell activation and increase antigen presentation on DCs." (PMID 30991681, 2019). "TLR9 was upregulated in HPV+ OPSCC cell lines, which may represent a cellular response to viral infection." (PMID 29416610, 2018). "TLR9 activation in pDCs results in the phosphorylation and nuclear translocation of transcription factors IRF3 and IRF7, which induce IFNα/β expression in response to viral infection and DNA sensing." (PMID 28861085, 2017). "Alternatively, IFN induction during viral infection is possible through TLR7 and TLR9 in DCs." (PMID 28163697, 2016). "TLR-9 expression is upregulated after HBV infection, which may result in stimulation of B cells to switch isotype to IgG2a against viral infection." (PMID 25892855, 2015). "Toll-like receptor 9 (TLR9) recognizes unmethylated 2′-deoxyribo(cytidine-phosphate-guanosine) (CpG) dinucleotide motifs in viruses and is of importance in the immunological defense against viral infections." (PMID 25097674, 2014). "Endosomal TLR3, TLR7, TLR8, TLR9 are specialized in the sensing of nucleic acids produced notably during viral infections." (PMID 24302927, 2013). "Following viral infection on day 14, production of IFN-β was restored by day 21 (a week after viral challenge) in Balb/c mice, but there was a significant reduction in IFN-β production in TLR-9-/- mice." (PMID 21810214, 2011). "These current findings suggest that restoring mitochondrial homeostasis or inhibiting TLR9 signaling could serve as potential targets for developing non-specific therapeutic strategies against viral infections." (PMID 40366175, 2025). "Alongside other innate receptors, TLR9, expressed by plasmacytoid dendritic cells, macrophages, B cells, and T-cells, produces type I interferon (IFN) and pro-inflammatory cytokines that are crucial for controlling viral infections and enhancing innate and adaptive memory responses." (PMID 39123407, 2024). "In conclusion, we have developed p54 (viral antigen) and CpG (a TLR-9 agonist) co-loaded PLGA NVs coated with CpG and mannose co-modified RBC membrane, which could be served as an effective and safe manner to boost protective immunity against virus infection." (PMID 36463277, 2022). "The results of our study suggest that the activation of TLR9-dependent signaling pathway is further strengthened through immunization with the recombinant baculovirus, which ultimately lead to secretion of IFN in host immune organs to confer protection against viral infection." (PMID 28757575, 2017).
viral infection (continued). "Besides, selected probiotic strains also showed no NF‐κB activity via TLR5 and TLR9, thus excluding other TLR signalling, since lactic acid bacteria and bifidobacteria do not possess LPS (TLR4 signalization) and the remaining TLRs are associated mainly with viral infections." (PMID 32945079, 2021). "From these findings we conclude that Siglec-H controls TLR-9-dependent, but not TLR-7 dependent inflammatory responses after virus infections and regulates chemokine responsiveness of pDCs." (PMID 34497606, 2021). "Circulating pDCs mediate rapid and robust secretion of IFN-α following bacterial or virus infection through TLR7 and TLR9 by sensing either non-methylated DNA or RNA." (PMID 24312342, 2013). "However, B cells can be the dominant antigen-presenting cells that activate naive CD4+ T cells in certain circumstances, and B cells activated by TLR9 and TLR7 ligands in the context of viral infection are sufficient to induce Tfh development in the absence of DCs." (PMID 34197340, 2021). "Colocalization analysis of TLR9 and MyD88 to ER or endosomes in JIMT-1 CD44+/CD24−/low CICs showed that neither TLR9 nor MyD88 fully reaches endosomes in 4 h and 6 h respectively, whereas in the CD44−/CD24− non-CIC population localization became endosomal upon virus infection." (PMID 21079774, 2010).
Sepsis (111 papers, 2009 to 2026). Sepsis is defined as life-threatening organ dysfunction caused by a dysregulated host response to infection. "The TLR9 rs187084 and rs352162 polymorphisms can be utilized to assess the risk of sepsis and multiple organ failure in people who have had severe trauma." (PMID 38685971, 2024). "This miRNA facilitates cellular autophagy by downregulating TLR9 expression, thereby leading to protection against sepsis-associated AKI." (PMID 38756232, 2024). "TLR9 can modulate the survival and fate of neurons, as shown in an in vivo model of sepsis-associated encephalopathy, in which mice in the treated group exhibited increased neurodegeneration and TLR9 expression in cortical neurons." (PMID 38891900, 2024). "Here, using a preclinical model of sepsis, erythroid TLR9–deficient mice, in vitro studies, and studies in humans, we demonstrate that animal models can recapitulate key clinical features of sepsis and even provide insight into heterogeneous host responses." (PMID 39666381, 2024). "Our previous work confirmed that NETs induced METTL3‐mediated m6A modification of GPX4 via TLR9/MyD88/NF‐κB pathway in sepsis‐associated lung injury." (PMID 37715457, 2023). "Here, deficiency of TLR9 or overexpression of miR-342-5p was found to enhance autophagy and diminish the release of inflammatory cytokines in LPS-treated sepsis cellular models." (PMID 37085762, 2023). "Detection on clinical serum samples showed that BUN, SCr, and TLR9 were elevated and miR-342-5p level was suppressed in the serum of patients with sepsis-associated AKI." (PMID 37085762, 2023). "Deletion of the receptor attenuates SAKI, and the adoptive transfer of TLR9-deficient DCs has been demonstrated as a factor in increasing survival in sepsis." (PMID 36010680, 2022). "The TLR9 polymorphism also has a functional significance in sepsis and multiple organ failure in patients with blunt trauma injury." (PMID 32967147, 2020). "The aim of our study was to investigate the possible associations between expression of TLR2, TLR4 and TLR9 and occurrence of sepsis in patients treated with intensive induction chemotherapy for AML." (PMID 25412934, 2014). "The aim of this study was to investigate the associations between expression of TLR2, TLR4 and TLR9 and occurrence of sepsis in patients treated with intensive induction chemotherapy for AML." (PMID 25412934, 2014). "The experiments of this study demonstrated that TLR4-deficiency protected partly and TLR9- as well as CD14-deficiency protected completely from sepsis-induced vasoplegia." (PMID 22970242, 2012). "Reduced levels of TLR-9 are associated with decreased immunopathological response early during sepsis, which could be correlated with the reduced mortality initially." (PMID 40076895, 2025). "On the other hand, TLR9 is associated with sepsis-related anemia." (PMID 40102400, 2025). "We tested whether kidney mitochondrial DNA (mtDNA) contributes to IL-6 release in sepsis-associated AKI via Toll-like receptor 9 (TLR9)." (PMID 41355794, 2025). "A recent report linked PANoptosis to sepsis-associated encephalopathy, suggesting that cortical neuron PANoptosis could be orchestrated by toll-like receptor 9 via activation of p38–mitogen-activated protein kinase pathway." (PMID 40995563, 2025). "For example, the release of mitochondrial DNA and damage-associated molecular patterns (DAMPs) following injury, trauma or sepsis (especially within ECs) has been implicated in activating TLR9, inducing MAPK and NF-κB inflammatory pathways and disrupting the EC barrier via the targeting of HMGB1." (PMID 35955534, 2022). "TLR9 pathway is important sensors of damage-associated molecular patterns (DAMPs) and mediated cellular interaction between immune cells and host cells in sepsis." (PMID 35637949, 2022).